NES (nestin)
Diseases named in the same sentence as NES in open-access papers (continued):
Sharing a sentence is not in itself a finding about the gene and the disease.
pancreatic cancer (continued). "We provide evidence that G9a expression correlated with the expression of the stemness genes including CD133, nestin and Lrg5 and inhibition of G9a in pancreatic cancer cells attenuated CD133 expression suggesting a role of G9a in the regulation of stemness in this cancer." (PMID 27531902, 2016). "Interestingly, the levels of phosphorylation of endogenous ULK1 at both S405 and S415 in the same pancreatic cancer cell lines were significantly higher than those in normal human pancreatic ductal epithelial cells and human pancreatic nestin-expressing (HPNE) cells." (PMID 33654220, 2021). "In pancreatic cancer, transfection of nestin shRNA in PANC cells caused decreased metastasis in immunodeficient mice upon intrasplenic injection, suggesting that nestin may also be involved in metastasis." (PMID 31126068, 2019). "Hypoxia increases TGF-β levels in pancreatic cancer cells, and TGF-β in a Smad4-dependent manner increases nestin expression, resulting in increased tumor-cell migration and EMT." (PMID 35625561, 2022). "DSCR9 expression was also significantly downregulated in four pancreatic carcinoma cell lines, PANC-1, BxPC-3, MIAPaCa-2, and AsPC-1, compared to that in the human pancreatic nestin-expressing cell line hTERT-HPNE." (PMID 36789695, 2022). "This implies a significant role of nestin in the regulation of TGF- Induced EMT, thereby serving as a potential treatment for pancreatic cancers." (PMID 33919917, 2021). "Furthermore, nestin targeting via small interfering RNA (siRNA) has a tumor inhibitory effect in vivo via the inhibition of tumor angiogenesis in a mouse model of pancreatic cancer, suggesting that nestin could be a potential therapeutic target of tumor angiogenesis." (PMID 34503252, 2021). "Intriguingly, we show that GSTP1 is present at higher levels in pancreatic carcinoma cell lines (MIA PaCa-2, PANC-1, HPAF-II, AsPC-1, and BxPC-3) compared to normal Human Pancreatic Nestin-Expressing ductal cells (hTERT-HPNE)." (PMID 32526885, 2020). "PSCs enhance the cancer stem cell phenotype of pancreatic cancer cells by inducing the expression of genes such as ABCG2, Nestin and LIN28 leading to an enhanced radio-resistance of pancreatic cancer cells in in vitro and in vivo systems of pancreatic cancer." (PMID 26029109, 2015). "In comparison with that within human pancreatic nestin expressing cells, hTERT-HPNE, the expression of miR-488 showed to be dramatically reduced within four pancreatic tumor cells, PANC-1, BxPC-3, MIA PaCa-2, and Capan-1, more downregulated in MIA PaCa-2 and PANC-1 cells." (PMID 35343383, 2022). "Not surprisingly, depleting nestin expression via siRNA resulted in decreased cell growth of vascular endothelial cell lines along with decreased subcutaneous human pancreatic cancer cell growth in nude mice." (PMID 31126068, 2019). "Cancer stem cells markers such as ALDH1A1, ABCG2, and nestin are highly expressed in metastatic cancer cells compared to non-metastatic cancer cells in animal models of pancreatic cancer." (PMID 26029109, 2015). "In contrast, another study showed that nestin downregulation does not alter the in vitro or in vivo growth characteristics of two distinct pancreatic cancer cell lines." (PMID 24498263, 2014). "Nestin has also received attention as a cancer stem cell (CSC) marker in various tumor cells including CNS tumors, uterine and cervical cancer, prostate, bladder, head and neck, ovarian, testicular and pancreatic cancers as well as malignant rhabdoid tumors." (PMID 22580387, 2012). "Nestin, an intermediate filament protein, is an angiogenesis-specific marker, and its expression is detected in newly formed blood vessels within tumor tissues including pancreatic cancers; however, expression is not observed in intratumoral mature vessels." (PMID 33083606, 2020). "Moreover, only the single paraclone-derived pancreatic tumor, but not the corresponding small hepatic tumoral lesion showed weak Nestin expression." (PMID 30167093, 2018).
pancreatic cancer (continued). "Non-transformed human pancreatic nestin expressing (HPNE) and mutant KRAS G12D-transformed HPNE (HPNE-KRAS) cells were used in this study to evaluate the impact of alcohol in a defined cellular and genetic context relevant to the most common early mutation event in pancreatic cancer." (PMID 35454872, 2022). "In addition, the expression of three stemness markers of pancreatic cancer including CD133, nestin and Lgr5 was also up-regulated suggesting GEM treatment may stimulate the stem-like properties of cancer cells and enrich a population of cancer stem cells (CSCs) with high drug resistance." (PMID 27531902, 2016).
medulloblastoma (34 papers, 2007 to 2024). A malignant, invasive embryonal neoplasm arising from the cerebellum. "Cancer stem cells reside in specialized, anatomically distinct niches within the tumor microenvironment and medulloblastoma stem cells (Nestin+, Prominin+) are closely associated with capillaries in the perivascular niche." (PMID 33869004, 2021). "Loss of one copy of Dicer induced SHH medulloblastoma with a similar time of onset and penetrance in Dicerfloxed/+; Nestin-Cre+; Ptch1+/-; Cdkn2c+/- compared to Dicer+/+; Ptch1+/-; Cdkn2c+/- mice, 76.5% (39/51) versus 62% (31/50), respectively." (PMID 26091048, 2015). "Treatment with JQ1 strongly suppressed expression of SOX2, Nestin and Nanog, all genes associated with neural stem cells and medulloblastoma." (PMID 24796395, 2014). "Previous reports have also implicated the role of Nestin-expressing progenitors in medulloblastoma initiation." (PMID 24796395, 2014). "Another team has also shown the role of the perivascular niche in resistance to radiation in medulloblastoma through the activation of the Akt/mTOR pathway in perivascular nestin-expressing stem cells." (PMID 36430649, 2022). "Genetic ablation of TAA dramatically inhibited Nestin expression in medulloblastoma cells, resulting in reduced proliferation and a blockage of tumor growth." (PMID 34436033, 2021). "We verified that the stem culture condition increased the expression of well-established MBSC markers CD133, FUT4, SOX2, NESTIN in all cell lines compared to the expression in medulloblastoma cells cultured in the presence of serum." (PMID 32316671, 2020). "We profiled Tuj1 expression, in addition to the stem markers Nestin, Olig2 and Sox2 across a panel of 46 medulloblastomas." (PMID 31160565, 2019). "Of note, similarly to NOTCH1, BMI1 and Nestin are weakly expressed in Group 3 medulloblastoma primary tumors from D425 xenografted mice." (PMID 30297829, 2018). "We here report the role of Dicer and mature miRNAs during cerebellar development and SHH medulloblastoma genesis by conditional deletion of Dicer (Dicer cKO) in Nestin-positive neural progenitors." (PMID 26091048, 2015). "To assess their role in cerebellar and medulloblastoma (MB) development, we deleted the miR-17∼92 cluster family in Nestin-positive neural progenitors and in mice heterozygous for the Sonic Hedgehog (SHH) receptor Patched 1 (Ptch1+/−)." (PMID 24928431, 2014). "Extrapolating from another type of tumour, medulloblastoma, in humans, 30% of nestin-expressing medulloblastoma stem cells in the perivascular niche are proliferating, as compared to less than 1% of NSCs in subventricular zone (SVZ)." (PMID 23998913, 2013). "Nestin is an intermediate filament protein located in the cytoplasm of most brain cancer cells, although it has been detected in the nuclei of human neuroblastoma and medulloblastoma cell lines." (PMID 38925618, 2024). "Furthermore, Nestin knockdown in medulloblastoma cells significantly inhibited proliferation in vitro and in vivo, independent of apoptosis." (PMID 34572373, 2021). "To test this hypothesis, we used an established mouse model system, in which retroviral transfer of Shh to Nestin+ neural progenitor cells in the cerebella of mice induces medulloblastomas that have a very low incidence of metastatic dissemination." (PMID 25059231, 2014).
medulloblastoma (continued). "However, we have evidence that conditional, partial knock-out of Pten, SmoA1 +; Pten (LoxP/-); Nestin-cre +, accelerates medulloblastoma formation compared to controls, SmoA1 +; Pten (LoxP/-); Nestin-cre -." (PMID 20520772, 2010). "However, ectopic expression of either human c-MYC or MYCN (mutationally stabilized and wild-type) in conjunction with SHH expression in Nestin-expression progenitor cells generated SHH medulloblastoma at a significantly increased incidence compared with infection with RCAS-SHH alone." (PMID 28333115, 2017). "Medulloblastoma-associated CSCs selected by serum-free medium with bFGF and EGF can form 3 D spheroids and display enhanced self-renewal and highly co-expressed stem cell genes (Oct4, Nanog, Nestin, and Musashi-1) as well as anti-apoptotic genes (Bcl-2 and Bcl-XL)." (PMID 20718984, 2010). "Afterward, in CSN tumours other than glioblastoma, such as medulloblastomas, ependymomas, and oligodendrogliomas, it was confirmed that CSCs, marked with CD133 and Nestin, were closely located next to capillaries." (PMID 37370764, 2023). "NESTIN and ATOH1 were expressed in some medulloblastoma cell lines but also in other tumor cell lines." (PMID 27310018, 2016). "MB-DPs and MB-derived CD133/Nestin double-negative cells (MB-DNs) were isolated from medulloblastoma cell line Daoy." (PMID 24945311, 2014). "Control SmoA1 +; Pten (LoxP/-); Nestin-cre - animals developed medulloblastomas with classic histology (Data not shown)." (PMID 20520772, 2010). "Thus, by using the nestin/IGF-I mouse model, we accomplished our goal to target IGF-I overexpression to the neural precursors of the cerebellum, the potential medulloblastoma progenitor cells." (PMID 20214787, 2010). "Medulloblastomas from Ptc1+/- and Ptc1+/-/IGF-I Tg mice both express active IGF-IR, although with a different staining pattern probably reflecting the generalized expression of the nestin/IGF-I transgene in tumors from double mutants." (PMID 20214787, 2010). "In the present study, we cross-bred nestin/IGF-I Tg mice, in which transgene expression starts prenatally and is detectable in the cerebellar primordium as early as embryonic day 13, with Ptc1+/- mice, a faithful model of medulloblastoma recapitulating the histopathology of the human tumor." (PMID 20214787, 2010). "Moreover a recent report demonstrates that a rare population of Nestin-expressing progenitors (NEPs) reside in the cerebellum and exhibit decreased expression of DNA repair genes; upon aberrant activation of SHH signaling these NEP give rise to medulloblastoma tumors." (PMID 24796395, 2014).
neuroblastoma (28 papers, 2006 to 2025). Neuroblastoma (NB) is the most common solid, extracranial childhood tumor. "Additionally, the presence of the stem cell marker Nestin, associated with cancer cell aggressiveness and stemness, was observed in most primary neuroblastoma cells." (PMID 40552293, 2025). "The overexpression of Nestin is associated with aggressive neuroblastoma phenotypes." (PMID 38891878, 2024). "In contrast, the expression of PROM1, SOX2, and NESTIN, three neuroblastoma stem cell markers, exhibited a notable increase in all iLIN28B samples compared to their corresponding CTRLs." (PMID 40679030, 2025). "We performed qPCR to examine the mRNA abundance of the common neuroblastoma stem cell markers, Oct4, Nanog, and Nestin." (PMID 34206917, 2021). "Dual therapy of retinoic acid and proteasome inhibitor induced apoptosis, decreased stem cell markers such as Nestin, Sox2 as well as Oct4, and impaired neurosphere formation in neuroblastoma cell lines." (PMID 31191243, 2019). "Neuroblastoma cell lines contain tumor initiating cells which express stem cell markers such as Nestin and CD133." (PMID 26934655, 2016). "Flow cytometric analysis confirmed differences in the expression of MAP2, β-catenin, and PDGFRβ while all neuroblastoma cells were nestin positive." (PMID 22891161, 2012). "LA-N-5 neuroblastoma tumorspheres were positive for nestin by immunostain and all other tested neuroblastoma cell lines showed significant nestin expression." (PMID 19156211, 2009). "A Nestin-targeted oncolytic herpes simplex virus efficiently replicated within and killed neuroblastoma tumor initiating cells preventing their ability to form tumors in athymic nude mice." (PMID 19156211, 2009). "Ex vivo infection of neuroblastoma cells with a nestin-targeted oHSV resulted in death of tumor initiating cells as it prevented tumor development in animals." (PMID 19156211, 2009). "In this study we demonstrated that a nestin-targeted oHSV efficiently infected, replicated and killed neuroblastoma tumorsphere cells." (PMID 19156211, 2009). "Another study has demonstrated the presence of nestin in the nucleus of neuroblastoma cells by means of cell fractionation and immunoblotting, and other experiments have showed that nestin binds to nuclear DNA in cell lines with N-myc amplification." (PMID 16457706, 2006). "OTX‐2 is a promising predictive biomarker candidate, but its mechanisms need further investigation in neuroblastoma, as nestin expression is not significantly linked to patient survival." (PMID 38925618, 2024). "Neuroblastoma cell types can express nestin which is considered a stemness marker." (PMID 32489570, 2020). "Both ABCG2 and nestin have since been used as markers for putative CSCs in neuroblastoma." (PMID 26729169, 2015). "Finally, a nestin-targeted oHSV effectively replicated within and killed neuroblastoma tumor initiating cells as measured by prevention of tumorigenicity." (PMID 19156211, 2009). "Based on nestin expression in primary neuroblastoma tumors and tumorspheres, we hypothesized that a nestin-targeted oHSV would be effective in killing both differentiated and tumor initiating neuroblastoma cells." (PMID 19156211, 2009). "A recent analysis revealed that MEG3 transcriptionally inhibits the expression of Nestin, a well-known CSC marker in neuroblastoma, potentially inhibiting CSC development." (PMID 38891878, 2024). "Researchers have revealed that neuroblastoma contains a cell population with stem cell–like characteristics with increased expression of CSC markers, such as nestin, OCT4, CD133, and ALDH." (PMID 37991019, 2023). "Gene expression analysis of NSs by quantitative polymerase chain reaction (qPCR) of β-catenin, NeuroD1, SOX2, Nestin, β-tubulin 3, and DCX genes was compared between each group and the SHSY-5Y neuroblastoma (positive control for neuronal cells)." (PMID 36835256, 2023).
neuroblastoma (continued). "In another study, human neuroblastoma cell lines were injected subcutaneously into SCID mice, and their growth behavior and nestin as well as CD44 expression were analyzed." (PMID 34943921, 2021). "Nestin and ABCG2 are neural precursor markers and were some of the earliest markers used to describe CSCs in neuroblastoma." (PMID 26729169, 2015). "We surveyed a panel of neuroblastoma cell lines for subpopulations by assessment of stem cell marker (CD34, CD133, Nestin) expression, the presence of a verapamil sensitive side population and the ability to form clonal spheres." (PMID 19156211, 2009). "Other studies revealed that neuroblastoma cells express neural precursor markers including CD34, ABCG2, and nestin." (PMID 19156211, 2009). "Additionally, RT-PCR analysis of TUJ1, a neuronal differentiation marker, showed a significant increase, whereas NESTIN, a neural stem cell marker showed a significantly decreased expression in USP3-silenced neuroblastomas." (PMID 37170124, 2023). "The expression level of pro-proliferative Ki67 and cyclin D1 (CCND1) genes, as well as of MYCN and Nestin (controlling neuroblastoma aggressiveness), did not undergo any significant change in cells, independent of either 2D or 3D condition." (PMID 33230715, 2021). "In contrast to neuroblastoma cells, both non-tumorigenic neural cells and transgenic mouse embryos with overexpression of Vangl2 in nestin-expressing cells showed increased active β-catenin and reduced differentiation." (PMID 27036398, 2016). "The neural progenitor markers Nestin and CD34 are also expressed in neuroblastoma cells." (PMID 24116151, 2013). "Growth of LA-N-5 neuroblastoma cells as non-adherent, nestin positive, multi-potent tumorspheres was dependent upon γ-secretase and EGFR signaling, similar to neural stem cells." (PMID 19156211, 2009). "Four of eight human neuroblastoma cell lines formed tumorspheres in neural stem cell media, and all contained some cells that expressed neurogenic stem cell markers including CD133, ABCG2, and nestin." (PMID 19156211, 2009). "A reduced expression level of Oct4, SOX2 and NESTIN was found, whereas TrkA, TH, MAP2 and TUJ1 was increased in USP3-silenced cells, suggesting that USP3 downregulation might impair self-renewal capacity in neuroblastoma." (PMID 37170124, 2023).